HGF (hepatocyte growth factor)
Diseases named in the same sentence as HGF in open-access papers (continued):
Sharing a sentence is not in itself a finding about the gene and the disease.
gastric cancer (138 papers, 1996 to 2025). A primary or metastatic malignant neoplasm involving the stomach. "G6PD is highly expressed and activates the NF-κB signaling pathway, thereby promoting the production of hepatocyte growth factor (HGF) in gastric cancer-associated mesenchymal stem cells (GCMSCs)." (PMID 39859324, 2025). "In another study using pre-diagnostic plasma samples from gastric cancer patients, increased HGF levels associated with cancer risk 6 years or longer prior to diagnosis." (PMID 34888239, 2021). "This study aimed to elucidate the expression level of HGF-c-MET in gastric cancer patients and to investigate the prognostic and diagnostic value of HGF-c-MET." (PMID 32788873, 2020). "HGF and its receptor Met proto-oncogene receptor tyrosine kinase (c-Met) are implicated in the peritoneal metastasis of ovarian and gastric cancer." (PMID 32780245, 2020). "The mesenchymal-epithelial transition factor receptor (MET), which is activated by hepatocyte growth factor (HGF), is associated with promotion of gastric cancer cell proliferation, survival and migration." (PMID 29721214, 2018). "The MET signaling pathway plays a critical role in various cancers, and the disruption of the balance of MET and HGF has been implicated in the etiology and progression of multiple cancers, including gastric cancer." (PMID 23554766, 2012). "Moreover, in gastric cancer, HGF and c-MET have been implicated in the accumulation of Tregs in peripheral blood." (PMID 40281554, 2025). "Furthermore, in gastric cancer, HGF and c-MET were implicated in Treg accumulation in peripheral blood." (PMID 39664377, 2024). "Thus, the expression of HGF was associated with an invasive and/or metastatic phenotype of gastric cancer cells." (PMID 35328253, 2022). "It is reported that overexpression of HGF can cause renal cell carcinoma, gastric cancer, and HCC and may also stimulate the growth of hidden cancer cells." (PMID 34683124, 2021). "HGF is a useful biomarker to predict gastric cancer risk and may play potential role in primary prevention of gastric cancer." (PMID 32607415, 2020). "Persistent HP infection in the gastric mucosa may promote the production of cytokines, including HGF, in the microenvironment, which could be associated with tumor progression via stimulating c-Met signaling in gastric cancer cells." (PMID 32630328, 2020). "Supporting this mechanism, preclinical studies in MET-amplified NSCLC and gastric cancer have demonstrated that high extracellular HGF concentrations markedly impair the efficacy of MET-TKIs." (PMID 41268440, 2025). "The mesenchymal-epithelial cell transition factor receptor (MET) is a receptor for hepatocyte growth factor (HGF) that can be amplified in gastric cancer." (PMID 40296904, 2025). "Of interest, the pharmacological effect of MET-TKI for MET-amplified NSCLC and gastric cancer cells was predominantly reduced under HGF-enriched conditions; however, additional inhibition of active HGF overcame resistance." (PMID 40076928, 2025). "Studies in the human gastric carcinoma cell line GTL‐16 cells demonstrated that prolonged HGF/SF‐MET signalling led to both multiubiquitination (proteasomal targeting) and K63‐linked polyubiquitination (lysosomal routing) of GAB1 in a CBL‐dependent manner." (PMID 40550626, 2025). "The expression of c-MET in circulating monocytes of gastric cancer patients was identified, with monocyte-derived dendritic cells exposed to HGF exhibiting a regulatory phenotype." (PMID 39664377, 2024). "Our previous studies have demonstrated that in gastric cancer cells, the binding of c-Met to its ligand HGF leads to a decrease in the levels of phosphorylated Mst1/2, LATS1/2, and YAP/TAZ." (PMID 38634107, 2024). "In gastric cancer, the HGF (hepatocyte growth factor)-mediated overexpression of PHLDA2 is linked to apoptosis." (PMID 38921000, 2024).
gastric cancer (continued). "In 100 patients with gastric cancer, the expression of HGF and MET was higher in patients with more advanced disease as well as peritoneal metastasis showing that it plays an important role in epithelial-mesenchymal transition." (PMID 37046637, 2023). "The activation of the HGF/c‐Met pathway has been elucidated in various types of cancer including gastric cancer, non‐small lung cancer, and hepatic cancer." (PMID 36825580, 2023). "Uptake experiments in the four patient‐derived gastric cancer xenograft models suggested a low concentration of HGF (4%–7% ID/g)." (PMID 35292998, 2022). "For example, HGF siRNA packed in exosomes can be transported into gastric cancer cells, where it decreases tumor growth rates and blood vessels in vivo." (PMID 34109113, 2021). "Hepatocyte growth factor (HGF) has also been shown to upregulate heparanase expression at the transcriptional level in lung and gastric cancer cells." (PMID 34681753, 2021). "Blocking HGF derived from GCMSCs is a potential new therapeutic target for the treatment of gastric cancer." (PMID 33718248, 2021). "HGF derived from GCMSCs promoted glycolysis, proliferation, and metastasis of gastric cancer by upregulating c-Myc-HK2 signal." (PMID 33718248, 2021). "To further confirm that GCMSCs-derived HGF promoted tumor progression by upregulating HK2 in gastric cancer cells, we constructed a mouse tumor model." (PMID 33718248, 2021). "Blocking HGF derived from GCMSCs decreased proliferation, metastasis, and angiogenesis of gastric cancer cells in vivo." (PMID 33718248, 2021). "The immunohistochemical analysis outcomes demonstrated that HGF derived from GCMSCs upregulated Vimentin and downregulated E-cadherin in gastric cancer tissues." (PMID 33718248, 2021). "Overall, the data obtained herein indicated that GCMSCs-derived HGF promoted gastric cancer progression by upregulating HK2 in vivo." (PMID 33718248, 2021). "Noguchi and colleagues showed that binding HGF to its receptor increased angiogenesis in tumor cells, which ultimately leads to increased cell proliferation, migration, and invasion of gastric cancer cells." (PMID 34930225, 2021). "The relationship between high expression of fibroblast activation protein and HGF with angiogenesis and metastasis in gastric cancer has been reported." (PMID 34930225, 2021). "In this study, using in vitro and in vivo analysis, we assessed the impact of the HGF/c-Met pathway, involved notably in tumor angiogenesis, on Treg accumulation in patients with gastric cancer." (PMID 34771724, 2021). "Our results demonstrated GCMSCs-derived HGF reprogramed glucose metabolism of gastric cancer cells by regulating HK2." (PMID 33718248, 2021). "Here we show that Hepatocyte Growth Factor (HGF), a pro-tumoral and proangiogenic factor, and its receptor c-Met are involved in regulatory T cells (Treg) accumulation in the peripheral blood of gastric cancer (GC) patients." (PMID 34771724, 2021). "Here, both ADMA and SDMA were positively correlated with systemic hepatocyte growth factor (HGF), pivotal for gastric cancer development and progression." (PMID 34439753, 2021). "Sank-Uk Han reported that exposure of SNU-16 gastric cancer cells to HGF down-regulates the expression of E-cadherin, and induces morphological changes from epithelial to mesenchymal type." (PMID 33178597, 2020). "Enhanced HGF secretion strongly promoted proliferation, migration and invasion of the gastric cancer cells." (PMID 33143170, 2020). "Recently, it was reported that CAFs promote VM formation in HCC cells by secreting TGF-β and SDF1; CAFs-derived HGF promote vascularization in gastric cancer." (PMID 33153467, 2020). "Similar to ovarian and gastric cancer, the EMT regulators HGF/c-Met have also been implicated in the peritoneal dissemination of PDA." (PMID 32780245, 2020).
gastric cancer (continued). "Numerous preclinical and clinical studies have generated data on monoclonal antibodies against HGF/c-Met axis, which provide possible targets for development of gastric cancer treatments." (PMID 33195182, 2020). "The mutation of HGF and mRNA upregulation of c-MET were the most common type of HGF and c-MET gene alterations in gastric cancer database, respectively." (PMID 32788873, 2020). "The activation of the c-Met/HGF pathway plays an important role in the tumorigenesis of gastric cancer." (PMID 31395059, 2019). "It inhibited both HGF-dependent and HGF-independent c-Met phosphorylation in vitro in lung and gastric cancer cell lines and showed tumor regression in xenografts model." (PMID 30134579, 2018). "Increased HGF intensified malignant phenotype of both MET-unamplified gastric cancer cells and CAFs, then CAFs with intensified malignant phenotype facilitated the expression of HGF, thus building a positive crosstalk." (PMID 30158543, 2018). "While MET was positive in 122 cases (31.0%), 57 (46.7%) of which were PD-L1-positive, HGF was positive in 125 gastric cancer (31.7%) samples, 49 (39.2%) of which were PD-L1-positive." (PMID 29137273, 2017). "On the other hand, HGF expression seems to exhibit a limited clinical significance in PD-L1-positive gastric cancers." (PMID 29137273, 2017). "MET and HGF were expressed in 31.0% and 31.7% of gastric cancers, respectively, where approximately half of which were PD-L1 positive." (PMID 29137273, 2017). "This study reveals for the first time a function of gelsolin in the HGF/cMet oncogenic pathway, which leads to E-cadherin repression and cell scattering in gastric cancer." (PMID 27058427, 2016). "Similar to overexpression or gene amplification of MET, these findings support our results that HGF induce the resistance to HER2-target drug in HER2-posotive gastric cancer patients." (PMID 26716644, 2016). "In locally advanced gastric cancer, the prognostic values of HGF/MET expression in tumor tissue has also been investigated and found to be a poor prognostic factor in patients who were treated by surgical resection or chemotherapy." (PMID 26716644, 2016). "The IM95 gastric cancer cell line was included for comparative analysis since it exhibits autocrine HGF signaling and dependence on c-Met signaling in the absence of MET amplification." (PMID 26879245, 2016). "The mesenchymal-epithelial transition factor receptor (MET) is activated by hepatocyte growth factor (HGF) and multiple signal pathways are activated upon HGF induction to promote gastric cancer cell proliferation, survival, and migration." (PMID 26880889, 2016). "The involvement of HGF/c-Met pathway leads to the activation of PI3K/Akt signaling pathway in gastric cancer cells." (PMID 26795388, 2016). "In preclinical study, previous report indicated that HGF activation of MET receptors rescued HER2-amplifed gastric cancer cells from lapatinib-induced growth inhibition by re-stimulating the downstream pathways and restoring normal cell-cycle progression." (PMID 26716644, 2016). "Two negative phase III studies have recently been reported, which cast a shadow on the HGF/cMET pathway-targeted therapy for gastric cancer." (PMID 26880889, 2016). "NRP-1 is shown to participate as co-receptors in the activation of the VEGF/VEGFR2, EGF/EGFR and HGF/c-Met pathways, which play key roles in the proliferation and metastasis of gastric cancer cells." (PMID 26795388, 2016). "Significant differences were detected in preoperative HGF levels between the gastric cancer and control groups (391.0±68.4 vs. 193.3±52.0 pg/ml, respectively; P<0.0001)." (PMID 25592281, 2015). "Previous studies of gastric cancer have revealed that co-expression of hepatocyte growth factor (HGF) and c-Met has the potential to promote peritoneal dissemination, and that a high level of c-Met expression is involved in the mechanisms of liver metastasis." (PMID 25638174, 2015).
gastric cancer (continued). "In gastric cancers, for instance, the high expression of MET and HGF is associated with the development of metastases." (PMID 26435753, 2015). "In the present study, the clinical significance of the HGF/c-Met pathway in the assessment of gastric cancer progression was evaluated." (PMID 25592281, 2015). "In gastric cancer, HGF activation of c-Met receptors rescues cells from lapatinib-induced growth inhibition by restimulating the downstream pathways and restoring normal cell-cycle progression." (PMID 25588551, 2015). "In the present study, serological and immunohistological analyses of the expression of the HGF/c-Met pathway in gastric cancer were performed in order to establish its clinical significance in the assessment of disease progression." (PMID 25592281, 2015). "In the present study, serological and immunohistological analyses were conducted in order to evaluate the clinical significance of the expression of the HGF/c-Met pathway in assessing the stage of gastric cancer progression." (PMID 25592281, 2015). "In this report, a patient with gastric cancer that exhibited one of the highest baseline circulating HGF from a series of patients treated in a phase I trial with onartuzumab, experienced a complete and durable response." (PMID 25026301, 2014). "The ‘EGF- and HGF-dependent stimulation of metastasis in gastric cancer’ map revealed upregulation of HGF and its receptor MET." (PMID 24204627, 2013). "Previously, induction of COX-2 through the activation of the ERK2 signal pathway by HGF has been demonstrated in gastric cancer." (PMID 23878598, 2013). "Research has shown that the HGF/c-Met pathway is related to gastric cancer lymphangiogenesis, which directly or indirectly promotes lymph node metastasis through the VEGF-C/VEGF-D/VEGFR-3 axis." (PMID 24325214, 2013). "The regulation of gastric cancer cell lines by hepatocyte growth factor (HGF) and c-metproto-oncogene (c-Met) has been described recently." (PMID 22018031, 2011). "Circulating HGF has previously been reported to be elevated in serum from patients with other cancers including head and neck squamous cell, breast, colorectal and gastric cancers." (PMID 21390244, 2010). "In a separate study, HGF/c-Met signaling enhanced gastric cancer cell proliferation and increased uPA synthesis and activity." (PMID 19497102, 2009). "Overall, these results suggest that ROS are involved uPA regulation in control of tumor invasion and metastasis by cytokines, such as HGF in gastric cancer cells." (PMID 19497102, 2009). "Stimulation of c-Met-overexpressing gastric cancer cells with HGF significantly reduced the basal level of ROS in a dose-dependent manner." (PMID 19497102, 2009). "Of 104 patients with primary gastric cancer, 35 (33.7%) showed an aberrant increase in the circulating level of HGF." (PMID 9043023, 1997). "Expression of HGF was also evaluated in a study of gastric cancer." (PMID 40076928, 2025). "Notably, treatment with an anti-HGF antibody reduced the number of circulating Tregs expressing c-MET in gastric cancer patients, underscoring HGF’s role in promoting Treg accumulation indirectly through c-MET-expressing monocytes." (PMID 40281554, 2025). "Interestingly, treatment with an anti-HGF antibody reduced circulating Tregs among gastric cancer patients, highlighting the role of HGF in fostering Treg accumulation indirectly via c-MET-expressing monocytes." (PMID 39664377, 2024). "Additionally, EGFR in exosomes secreted from gastric cancer cells can transfer to liver stromal cells and enhance hepatocyte growth factor (HGF) via reducing miR-26a/b expression." (PMID 38495881, 2024). "Moreover, we found that HGF, similarly to bovine serum, did affect the proliferation of GC cells, confirming an important role of HGF in the growth of gastric cancer." (PMID 35328253, 2022). "Four patient‐derived xenografts of gastric cancer (c‐Met‐positive, HGF unknown) were also used in the same experiments." (PMID 35292998, 2022).
gastric cancer (continued). "HGF is one of the better-known factors in gastric cancer biology." (PMID 35328253, 2022). "Similarly, co‐expression of c‐MET and its ligand HGF was shown to predict peritoneal dissemination in gastric cancer." (PMID 34542930, 2021). "Furthermore, we demonstrated that HGF derived from GCMSCs promoted the proliferation and metastasis of gastric cancer cells by upregulating HK2." (PMID 33718248, 2021). "HGF siRNA can be transported to cancer cells using exosomes, which can down-regulate expression of HGF, thereby inhibiting the proliferation and migration of gastric cancer cells." (PMID 35111071, 2021). "Induction of HGF/cMet inhibition resulted in phase arrest of cell cycle and apoptosis in numerous cancer cell species, including primary effusion lymphoma, multiple myeloma, and gastric cancer." (PMID 34683124, 2021). "Blocking GCMSCs-derived HGF decreased the progression of gastric cancer in vivo." (PMID 33718248, 2021). "Finally, rilotumumab, an anti-HGF antibody, decreases the percentage of circulating Treg in gastric cancer patients." (PMID 34771724, 2021). "HGF is overexpressed in gastric cancer, as well as many other cancers." (PMID 33050602, 2020). "Our integrative analyses of HGF-c-MET signaling pathway in human gastric cancer patients based on public cancer databases (TCGA and GEO), aiming to better define the characteristics, extent and prognostic prediction of HGF-c-MET signaling pathway involved in gastric cancer." (PMID 32788873, 2020). "Similarly, MACC1 and HGF levels were correlated with the survival rates of gastric cancer patients, while a different study also demonstrated that MACC1 promotes the progression of epithelial ovarian cancer via the HGF/c-Met signaling pathway." (PMID 33425885, 2020). "All components work together in the microenvironment and affect the tumorigenesis of gastric cancer, such as HGF which could not only be autocrine by tumor cells themselves but also participated in paracrine communication." (PMID 32788873, 2020). "Therefore, the up-regulation of HGF promotes gastric cancer as well as liver metastasis, while down-regulation of HGF suppresses liver metastasis." (PMID 32012717, 2020). "In gastric cancer, both HGF and c-MET contribute and participate in oncogenic pathways." (PMID 30360560, 2018). "Hepatocyte growth factor (HGF) was found to be expressed in human gastric cancer tissue." (PMID 28350359, 2017). "In the experiments, we investigated the effect of PKG II on HGF induced biological activities of gastric cancer cell, including the activation of c-Met, its downstream signaling of MAPK, PI3K/Akt and STAT mediated pathways, and the changes of proliferation, migration and apoptosis." (PMID 27147579, 2016). "The HGF/c-Met pathway is involved in the progression of gastric cancer by activating Akt pathways." (PMID 26795388, 2016). "In this study, adding HGF to lapatinib treatment in MET-overexpressed HER2 gastric cancer cells not only activated MET, but also led to restimulation of downstream effectors AKT and ERK1/2 even in the presence of lapatinib, although phosphorylation of HER2 and EGFR continued to be suppressed." (PMID 26716644, 2016). "In our study, serum levels of HGF were different by HER2 expression of gastric cancer tissues." (PMID 26716644, 2016). "Therefore, the preoperative serum HGF levels in patients with gastric cancer represent a potential predictive factor for disease progression, as observed in colon cancer." (PMID 25592281, 2015). "Although elevated serum HGF levels in patients with gastric cancer had been previously reported, the present study aimed to determine whether this factor may be used in the assessment of disease progression." (PMID 25592281, 2015). "HGF may also play a pivotal role in the regulatory circuit between gastric cancer cells and stromal fibroblasts, and neutralization of HGF inhibits both activation and tumor-promoting properties of CAFs." (PMID 28536400, 2015).